ATM (ATM serine/threonine kinase)
Diseases named in the same sentence as ATM in open-access papers (continued):
Sharing a sentence is not in itself a finding about the gene and the disease.
bladder cancer (55 papers, 2008 to 2025). "Regarding radiotherapy, DAB2IP loss promotes bladder cancer cells resistance to ionizing radiation (IR) by increasing the expression of ataxia‐telangiectasia mutated (ATM) and the activation of NF-κB pathway and p38MAPK." (PMID 38902547, 2024). "Investigations on bladder cancer have revealed a significantly higher incidence of ATM mutations and associated somatic copy number alterations in white and black populations compared to Asians." (PMID 39541191, 2024). "Although confirmation of this mutation is needed in large studies, this finding further substantiates ATM's role in bladder cancer risk." (PMID 36816149, 2023). "Recent emerging data indicated that bladder cancers harbouring ATM mutations are susceptible to increased sensitivity to 29 drugs including cisplatin, IGF‐1R inhibitor and BMS‐536924." (PMID 36056635, 2022). "According to their ATM gene mutation status, bladder cancer patients with mutation data treated with ICIs (anti-pd-1/pd-l1 therapies) (n = 210) were divided into ATM-MT and ATM-WT groups, and then KM analysis was performed." (PMID 32922441, 2020). "Since DNA repair gene defects play an important role in the occurrence, development, therapeutic response and prognosis of bladder cancer, we further explored the role of ATM mutations in DDR pathways." (PMID 32922441, 2020). "ATM mutations resulted in increased bladder cancer sensitivity to 29 drugs (P < 0.05), including cisplatin and BMS-536924, an IGF-1R inhibitor." (PMID 32922441, 2020). "We first explored the role of ATM mutations in bladder cancer by evaluating the associations between the gene mutation status and clinical phenotypes in the immunotherapy cohort and TCGA-Bladder cancer cohort." (PMID 32922441, 2020). "To evaluate the relationship between ATM gene mutations and the prognosis of bladder cancer patients who received ICI treatment, we collected an immunotherapy cohort with clinical data and mutational data." (PMID 32922441, 2020). "Compared to the ATM-WT group, ARID1A and TTN mutations were significantly upregulated in the ATM-MT group in the immunotherapy cohort and the TCGA-Bladder cancer cohort, respectively." (PMID 32922441, 2020). "We found that ATM mutation resulted in increased bladder cancer sensitivity to 29 drugs, including cisplatin (P < 0.05), BMS-536924, an IGF-1R inhibitor (P < 0.05), motesanib, a VEGFR inhibitor (P < 0.05), and WHI-P97, a JAK inhibitor (P < 0.05)." (PMID 32922441, 2020). "ATF3 also suppresses bladder cancer metastasis through promoting gelsolin-mediated actin remodeling and maintains genomic stability by activating ataxia telangiectasia mutated (ATM) signaling." (PMID 28860159, 2017). "Pretreatment with genistein sensitized BDEC and bladder cancer cell lines to HCPT-induced DNA damage by the synergistic activation of ataxia telangiectasia mutated (ATM) kinase." (PMID 23365634, 2013). "Genes like BAP1 and ATM showed high biallelic loss in kidney and bladder cancers." (PMID 40420266, 2025). "The finding for the association between ATM V2424G and bladder cancer risk is worth noting." (PMID 36816149, 2023).
bladder cancer (continued). "The same report indicated an inactivating mutation of ATM gene in 14% of bladder cancers." (PMID 36056635, 2022). "However, previous studies revealed that ATM mutation was an indicator for poor overall survival in bladder cancer compared with the wild‐type." (PMID 36056635, 2022). "In bladder cancer, ATM/RB1 mutations predicted poorer survival." (PMID 36056635, 2022). "Likewise, ATM-p73 axis regulated by circLIFR/MutSα was an important determinant of chemotherapy susceptibility in bladder cancer." (PMID 33874956, 2021). "To determine how ATM mutations enhance the immunogenicity of bladder cancer and activate antitumor immunity, we compared the expression differences in 74 immune-related genes (antigen presentation/stimulation/inhibition) and immune cell-related genes between the ATM-MT group and AMT-WT group." (PMID 32922441, 2020). "Finally, by analyzing the GDSC database, we found that ATM mutations resulted in increased bladder cancer sensitivity to 29 drugs, including cisplatin, the first-line treatment for bladder cancer, and BMS-536924, an IGF-1R inhibitor." (PMID 32922441, 2020). "In addition, we downloaded the TCGA-Bladder cancer cohort somatic mutation and survival data from the Genomic Data Commons (see footnote 1) and similarly performed KM analysis according to the ATM mutation status." (PMID 32922441, 2020). "Therefore, we aimed to elucidate the association between ICIs in bladder cancer and ataxia telangiectasia mutated (ATM), a core component of the DNA repair system." (PMID 32922441, 2020). "Therefore, among bladder cancer patients treated with ICIs, patients with ATM gene mutation exhibited a better prognosis than those with ATM-WT." (PMID 32922441, 2020). "Additionally, we analyzed the effect of ATM mutation on the sensitivity of bladder cancer cells to drug therapy in the GDSC cohort." (PMID 32922441, 2020). "To confirm our hypothesis, we further analyzed the effect of ATM mutations on bladder cancer by evaluating drug sensitivity data from the GDSC database." (PMID 32922441, 2020). "However, our attempt to explain the mechanism of ATM mutation promoting immunotherapy for bladder cancer was based on a hypothetical model, which need to be further verified." (PMID 32922441, 2020). "ATM mutations increased bladder cancer sensitivity to 29 drugs (p < 0.05), including cisplatin." (PMID 33266377, 2020). "A recent report has shown that olaparib induces ROS in bladder cancer cells, therefore, we also determined whether ROS levels were elevated in our olaparib-treated ATM-deficient A549 cells using a fluorescence-based assay." (PMID 31481733, 2019). "An immunosuppressive AtM B cell subset was identified in a mouse model of bladder cancer, and depletion of this subset delays cancer progression, indicating that AtM B cells promote bladder cancer progression." (PMID 39744696, 2025). "Meanwhile, ATM alterations exhibited biallelic alterations in multiple cancers, but the proportions were generally lower, except in breast and bladder cancers, both at 66.7%." (PMID 40420266, 2025). "The most frequently mutated genes in ordinary bladder cancer are TP53x, KMT2A, SPTAN1, ERBB2, CREBBP, FAT1, ATM, and KMT2C." (PMID 36779496, 2023). "The expression patterns of ATM/ERBB2 mRNAs were also investigated at the protein level in the TCGA‐bladder cancer cohort." (PMID 36056635, 2022).
bladder cancer (continued). "We investigated the balancing mechanism between HER2 and ATM at protein and mRNA levels using bladder cancer TCGA cohort from the cBioPortal database." (PMID 36056635, 2022). "We sought to determine the expression of HER2 and ATM at the protein and mRNA levels in bladder cancer cohorts to understand their relationship and investigate their impact on patient survival and cancer aggressiveness." (PMID 36056635, 2022). "The main limitation of our study is that it was a retrospective observational study and further analyses with larger sample size are needed to investigate the relation between HER2, ATM and bladder cancer prognosis." (PMID 36056635, 2022). "The aim of the current study was to describe an integrative analysis of HER2 and ATM interaction using the Cancer Genome Atlas (TCGA) bladder cancer cohorts to highlight the importance of both genes as potential prognosticators for bladder cancer patients." (PMID 36056635, 2022). "This transcriptomic and proteomic‐based analysis provides evidence of a strong correlation between inhibition of HER2 expression and increased ATM expression in bladder cancer." (PMID 36056635, 2022). "Next, we sought to analyse the functional enrichment pathways of the ATM/HER2 using the TCGA‐Bladder cancer cohort." (PMID 36056635, 2022). "In order to understand how the ATM/HER2 status can affect the prognosis for bladder cancer patients, we investigated the overlapping PPI between the HER2 and ATM pathways using Reactome pathway database tool." (PMID 36056635, 2022). "We analyzed the relationship between ATM mutations and gene mutations in the eight DDR-related pathways in the immunotherapy cohort, TCGA-Bladder cancer cohort and GDSC-Bladder cancer cell line dataset." (PMID 32922441, 2020). "We found that the ATM-MT bladder cancer patients had better benefits from ICI therapy and showed a higher mutation load and immunogenicity." (PMID 32922441, 2020). "In conclusion, we found that ATM-MT bladder cancer patients showed greater benefit from ICI therapy than ATM-WT patients in the immunotherapy cohort and TCGA-Bladder cancer cohort." (PMID 32922441, 2020). "Next, we analyzed the functional enrichment pathways of the ATM-MT and ATM-WT groups in the TCGA-Bladder cancer cohort and GDSC dataset by GSEA." (PMID 32922441, 2020). "In fact, the RRx-001 agent, by exposing the bladder cancer cells to reactive oxygen species, can induce oxidative damage determining ATM phosphorylation and γH2AX activation." (PMID 30786932, 2019). "Of the missense variants examined in fishing cat gene orthologs for human bladder cancer risk genes, DNA damage repair pathway genes BRCA1/2, CHEK2, and ATM all showed higher missense variant prevalence in the cohort; however, only BRCA2 showed a skewed distribution in TCC over healthy cats." (PMID 38580653, 2024). "Additionally, the most frequently mutated genes in ordinary bladder cancer are KMT2C, ATM, FAT1, CREBBP, ERBB2, SPTAN1, and KMT2A." (PMID 39399176, 2024).
bladder cancer (continued). "Pathogenic mutation rate of ATM was significantly higher among aggressive bladder cancer patients (7/208 = 3.37%) than nonaggressive bladder cancer patients (4/1487 = 0.27%), OR = 12.91 (95% CI: 3.71–44.50), p = 8.15E‐05." (PMID 36816149, 2023). "Interestingly, genistein also sensitizes bladder cancer cells to hydroxycamptothecin treatment in vitro and in vivo through ATM/NF-κB/inhibitor of NF-κB kinase (IKK)-mediated apoptosis." (PMID 33996570, 2021). "The upregulated genes mostly play role in cell cycle and proliferation pathways such as G2/M damage checkpoint regulation, cell cycle control of chromosomal replication, ATM signaling, hereditary breast cancer signaling, bladder cancer signaling and HIF1 signaling pathways." (PMID 32998690, 2020). "In addition, we explored the differences in pathway activation between the ATM-MT bladder cancer patients and ATM-WT patients through functional enrichment analysis to explain the effect of ATM on the efficacy of ICIs and the tumor microenvironment (TME)." (PMID 32922441, 2020). "From a collected immunotherapy cohort (n = 210) and The Cancer Genome Atlas (TCGA)-Bladder cancer cohort, which were both retrieved from publicly available resources, we performed a series of analyses to evaluate the prognostic value and potential mechanism of ATM in bladder cancer immunotherapy." (PMID 32922441, 2020). "Above all, ATM-MT bladder cancer cells are likely to promote the infiltration of cytotoxic cells and Th17 cells into tumor tissues by secreting relatively large amounts of chemokines, such as CCL5, to activate dendritic cells and promote the therapeutic effect of immune checkpoint inhibition." (PMID 32922441, 2020). "Therefore, ATM-MT bladder cancer cells are likely to downregulate the activity of the insulin-like growth factor receptor pathway by upregulating AGE1 gene expression, thereby inhibiting the invasion and metastasis of bladder cancer and improving survival." (PMID 32922441, 2020). "Third, we propose that ATM-MT bladder cancer patients may benefit from the combined application of ICIs and IGF-1R inhibitors, which opens a new approach for clinical treatment, but further experimental confirmation is still needed." (PMID 32922441, 2020). "Additionally, we found that ATM-MT bladder cancer cells were likely to downregulate the activity of the insulin-like growth factor receptor pathway by upregulating AGE1 gene expression, thus promoting the efficacy of ICIs." (PMID 32922441, 2020). "Our results demonstrate the importance of ATM as a prognostic signature in bladder cancer and reveal that ATM may impact the effects of ICIs by acting on the tumor immune microenvironment." (PMID 32922441, 2020). "In addition to ATM, germline mutations in MRE11 has been shown to be predictive of radiotherapy response in bladder cancer, while inherited defects in DSB repair genes NBS1 and Lig4 have been linked to fatal complications from low doses of radiotherapy." (PMID 28055970, 2017). "To define the events proximal to DNA damage that might contribute to the immunomodulatory effects of cisplatin versus carboplatin, we treated 5637 bladder cancer cells with increasing concentrations of the platinum drugs and probed the impact on DNA damage transducers ATM and ATR." (PMID 38280376, 2024).
bladder cancer (continued). "Second, while we verified that ATM-MT bladder cancer cells are likely to downregulate the activity of the insulin-like growth factor receptor pathway by upregulating AGE1 gene expression, the functional pathway analysis of ATM mutations needs to be further verified in vitro and in vivo." (PMID 32922441, 2020). "Finally, this study focused on the prognostic value rather than the predictive value of ATM mutations in patients with bladder cancer who received ICI therapy." (PMID 32922441, 2020). "However, germline alterations in other well-known DNA repair genes such as BRCA1, BRCA2, or ATM have not been clearly linked to bladder cancer risk." (PMID 28346378, 2017). "However, we also identified mutations in two other genes not reported in COSMIC for bladder cancer, ATM and FBXW7." (PMID 23593348, 2013). "We recently highlighted the interplay between ATM (one of the homologous recombination factors) and ERBB2 in bladder cancer patients." (PMID 37474724, 2023). "Understanding the molecular interactions between ATM and HER2 is particularly important in the prognosis and the treatment planning of bladder cancer patients." (PMID 36056635, 2022). "The process of bladder cancer development and progression involved activation of oncogenes, such as HER2, and inactivation of tumour suppressor genes, such as ATM." (PMID 36056635, 2022). "In this cohort (Cohort three), 10 normal bladder mucosae samples, 58 normal looking bladder mucosae surrounding cancer and 165 primary bladder cancer samples were profiled for ERBB2 and ATM mRNA expression using Illumina human‐6 v2.0 expression beadchip." (PMID 36056635, 2022). "Choudhry and colleagues examined protein expression of MRE11, RAD50, NBS1, ATM, and H2AX by immunohistochemistry in pretreatment tumor specimens from 179 bladder cancer patients receiving radical radiotherapy." (PMID 26198537, 2015). "As MRE11, NBS1, RAD50, ATM, and H2AX interact with each other to facilitate DSB damage signalling, we hypothesized that there may be a gene dosage effect in our study, with subjects with increasing numbers of high risk alleles having an increased risk of bladder cancer." (PMID 18638378, 2008). "A trend of higher carrier rate of ATM V2424G in aggressive bladder cancer patients (2/208 = 0.96%) than nonaggressive bladder cancer patients (2/1487 = 0.13%) was observed, p = 0.08." (PMID 36816149, 2023). "The drug KU-55933 was identified as an inhibitor of ATM and was reported to suppresses cell proliferation and induce apoptosis, as well as increasing the TMZ responsiveness and sensitizing radioresistant bladder cancer cells." (PMID 36836919, 2023). "Data identified that in the low HER2 cohort and different ATM levels (high/low); ABL1, SMAD4, RB1 and PARP1 were significantly upregulated and AKT1, AKT2, TSC2, RPTOR and mTOR were significantly downregulated in bladder cancer." (PMID 36056635, 2022). "Another study showed that elevated ATM expression, induced by DAB2IP-knockdown [disabled homolog 2 interactive protein (DAB2IP)—a tumor suppressor gene] might represent a key event in bladder cancer radioresistance." (PMID 33224881, 2020).